AGTPBP1 (ATP/GTP binding carboxypeptidase 1)
Diseases named in the same sentence as AGTPBP1 in open-access papers (continued):
Sharing a sentence is not in itself a finding about the gene and the disease.
lung adenocarcinoma (1 paper, 2020). A carcinoma that arises from the lung and is characterized by the presence of malignant glandular epithelial cells. "However, suppressive effect of AGTPBP1 expression on lung adenocarcinoma was suggested by the analysis of LUAD-TCGA datasets without considering KRAS mutation." (PMID 33276627, 2020).
pancreatic cancer (1 paper, 2024). "Subsequently, we examined the expression of AGTPBP1 in 179 pancreatic cancer and 171 pancreatic normal tissues by GEPIA, an online gene expression interaction analysis database based on the TCGA database and GTEx project." (PMID 39129004, 2024). "Our findings revealed that the expression of AGTPBP1 was significantly higher in pancreatic cancer cells (PANC-1 and HPAF-II) compared to HPDE6-C7 cells." (PMID 39129004, 2024). "Our study demonstrated for the first time that AGTPBP1 is highly expressed in pancreatic cancer tissues and cells and its expression has a close relationship with tumor location." (PMID 39129004, 2024). "Our study investigated the expression and roles of AGTPBP1 in pancreatic cancer for the first time." (PMID 39129004, 2024). "The Spearman correlation analysis showed AGTPBP1 was positively correlated with the expression of MYLK and MAP1A in pancreatic cancer tissues by GEPIA analysis." (PMID 39129004, 2024). "Next, we investigated the expression of AGTPBP1 in human normal pancreatic ductal epithelial cells (HPDE6-C7) and pancreatic cancer cells such as PANC-1 and HPAF-II using RT-qPCR." (PMID 39129004, 2024). "According to the GEPIA analysis based on TCGA, similar to AGTPBP1, the expression of MYLK and MAP1A in pancreatic cancer tissues was significantly upregulated (P < 0.05)." (PMID 39129004, 2024).
pancreatic ductal adenocarcinoma (1 paper, 2024). An infiltrating adenocarcinoma that arises from the epithelial cells of the pancreas. "In contrast, within pancreatic ductal adenocarcinoma cells, AGTPBP1 was primarily observed in the cytoplasm (arrow indicated), with only rare occurrences of nuclear localization." (PMID 39129004, 2024).
cancer (4 papers, 2009 to 2024). A tumor composed of atypical neoplastic, often pleomorphic cells that invade other tissues. "As the tumor infiltrating of immune cells influences the outcome of cancer by altering the balance of suppressive versus promotive tumor microenvironment, this result suggests the important role of AGTPBP1 in immune microenvironment regulation." (PMID 33276627, 2020). "We compared cancer cell growth between control and AGTPBP1-silenced A549 cells for five days." (PMID 33276627, 2020). "Moreover, the alteration frequency of AGTPBP1 was 4% in the TRAcking Cancer Evolution through therapy (TRACERx) dataset and 3% in the Broad Institute dataset." (PMID 33276627, 2020). "Moreover, drug resistance of AGTPBP1-silenced A549 cells was intensified by treatment with the two commonly used cancer chemotherapeutic drugs, doxorubicin and cisplatin." (PMID 33276627, 2020). "Thus, these previous findings suggest that AGTPBP1 may play a role in cancer by affecting microtubule stability and tubulin deglutamylation." (PMID 39129004, 2024). "In the CPTAC dataset, AGTPBP1 protein expression was downregulated in primary LUAD regardless of the clinicopathological characteristics, including cancer stage, the patient’s race, gender, age, weight, and tumor grade." (PMID 33276627, 2020). "AGTPBP1 expression was significantly downregulated regardless of the stage of cancer in both LUAD and LUSC." (PMID 33276627, 2020). "However, the function of AGTPBP1 in cancers has not been focused on." (PMID 39129004, 2024). "However, the function of AGTPBP1 in cancers has not yet been fully understood." (PMID 39129004, 2024).
neurodegenerative disease (2 papers, 2020 to 2021). A disorder of the central nervous system characterized by gradual and progressive loss of neural tissue and neurologic function. "Whole exome sequencing studies on CONDCA patients have identified different damaging biallelic variants of the AGTPBP1 gene, linking AGTPBP1 loss of function to human neurodegenerative diseases." (PMID 34572343, 2021).
tumor (2 papers, 2020 to 2024). "Our findings indicated a strong correlation between AGTPBP1 expression and tumor location, particularly with higher expression levels in tumors at the tail of the pancreas." (PMID 39129004, 2024). "There was a significant decrease in the sh-AGTPBP1 group in tumor size compared with their control sh-NC counterparts (P < 0.05)." (PMID 39129004, 2024). "Knockdown of AGTPBP1 can attenuate the xenograft tumor growth and new blood vessel formation in nude mice." (PMID 39129004, 2024). "The higher expression of AGTPBP1 correlated with tumor located at the tail of the pancreatic body and lower expression at the pancreatic head and hook." (PMID 39129004, 2024). "= −0.119, p = 7.95 × 10−3), indicating that AGTPBP1 was probably expressed by the tumor-infiltrating immune cells." (PMID 33276627, 2020). "The tumor-suppressive effects of AGTPBP1 suggest that the expression of AGTPBP1 is reduced during lung oncogenesis." (PMID 33276627, 2020). "In this context, AGTPBP1 expression exhibited relatively high correlation with specific gene marker of CD8+ T cells, monocytes, tumor-associated macrophages, M1 and M2 macrophages, Tregs, and exhausted T cells in LUAD." (PMID 33276627, 2020). "Our results confirmed that AGTPBP1 knockdown could attenuate the proliferation of PC cells, tumor growth, and angiogenesis." (PMID 39129004, 2024). "The effects of AGTPBP1 knockdown suggest the suppressive role of AGTPBP1 in tumor progression." (PMID 33276627, 2020). "In the TCGA dataset, AGTPBP1 expression negatively correlated with tumor purity in LUAD (cor." (PMID 33276627, 2020). "To further investigate the correlation between AGTPBP1 mRNA expression and diverse subsets of tumor-infiltrating immune cells in LUAD, we carried out correlation analysis using markers of T cells, B cells, monocytes, M1 and M2 macrophages, neutrophils, NK cells, and DCs." (PMID 33276627, 2020). "Therefore, AGTPBP1 expression showed a significant positive correlation with patient survival in multiple datasets of patients with NSCLC, suggesting a tumor-suppressive role of AGTPBP1." (PMID 33276627, 2020).
neurological disorders (1 paper, 2021). "Progressive advancement of the neurological disorders resulted in the death of 7 patients out of the 18 individuals carrying damaging variants of the AGTPBP1 gene." (PMID 34572343, 2021). "This raises questions regarding the potential role of AGTPBP1 in other human neurological disorders." (PMID 34572343, 2021). "The fact that the pathological characteristics of the pcd mutation share clear similarities with those of CONDCA patients indicates that AGTPBP1 function is essential to the development of neurological disorders not only in mice but also in humans." (PMID 34572343, 2021).
AGTPBP1 also shares sentences with these, for which no sentence is quoted: cerebellar ataxia (1 paper); cerebellar degeneration (1); ciliopathy (1); developmental delay (1); diabetic retinopathy (1); Failure to thrive (1); microcephaly (1); myopia (1); Neurodegeneration (1); pancreatic adenocarcinoma (1); retinal degeneration (1); retinitis pigmentosa (1).